MMP2 (matrix metallopeptidase 2)
Diseases named in the same sentence as MMP2 in open-access papers (continued):
Sharing a sentence is not in itself a finding about the gene and the disease.
infarction (14 papers, 2011 to 2024). A localised pathological necrosis of tissue resulting from obstruction of the blood supply usually by a thrombus, an embolus, or vascular torsion. "According to these observations, in our study, by analyzing the presence of cerebral lacunar infarcts detected by MRI, we demonstrate a positive and significant independent association between MMP-2, TIMP-1, TIMP-2, TIMP-3 and the presence of the lesions." (PMID 37959331, 2023). "Though the differences were rather discreet, it is still obvious that staining of MMP-2, MMP-9, and TIMP-1 in younger wound age groups was more intense in cases with an underlying infarction compared to those with injuries of other origins." (PMID 34041592, 2021). "MI and IPostC induced a parallel significant increase in MMP-2 in the plasma at three hours (MI-3h: p = 0.007; IPostC-3h: p = 0.011) and three days (MI-3d: p = 0.0004; IPostC-3d: p = 0.0003) post-infarction compared to the control group." (PMID 30650650, 2019). "RPO was able to reduce myocardial infarct size in cholesterol fed rats, despite increased activity of MMP2 in reperfusion found in normal rats." (PMID 21689423, 2011). "In a report on the change in miR expression in response to myocardial ischemia-reperfusion (IR) in the heart of the mouse, it was shown that miR-21 regulates the expression of matrix metalloproteinase 2 (MMP-2) in cardiac fibroblasts in the infarction zone via the PTEN pathway." (PMID 32337248, 2020). "Intravenous administration of bone marrow-derived MSCs after middle cerebral artery occlusion in a rat model resulted in increased activity of MMP-2 and vascular density, and in reduced infarction volume suggesting the important role of MMP-2 activity and MSCs in promoting angiogenesis." (PMID 27612636, 2016). "In the case of the cardiac aneurysm presented in this study, the most probable cause was cardiac injury, such as infarction, and the hypoxia that followed could be responsible for the strong expression of both MMP-9 and MMP-2, as well as the remodeling of the tissue." (PMID 39682376, 2024). "In a recent study from our group, we found that early elevations of matrix metalloproteinase (MMP)-2 in plasma correlated strongly with infarct size and left ventricular dysfunction in a STEMI population, indicating that MMP-2 might play an important role in IR-injury." (PMID 23405158, 2013). "Results were compared with sham and infarction groups with no MMP-2 inhibitors." (PMID 29670878, 2018).
mesothelioma (14 papers, 2012 to 2025). A usually malignant and aggressive neoplasm of the mesothelium which is often associated with exposure to asbestos. "In a study that included 236 mesothelioma patients and 161 healthy blood donors, carriers of at least one polymorphic MMP2 rs243865 allele had significantly lower risk for mesothelioma." (PMID 34572485, 2021). "We have previously shown high expression of FBN1 and FBN2 as well as MMP2 in association with high GREM1 expression in JP5 cells as well as in other mesothelioma cells." (PMID 29968778, 2018). "Metalloproteinases are strongly implicated in most of the dysregulated processes in cancer, such as tumor growth, metastasis and angiogenesis and are highly expressed in mesothelioma, particularly MMP2 and MMP9." (PMID 36232554, 2022). "MMP2 activity was similar in inflamed pleura and mesothelioma, but MMP9 activity was higher in inflamed pleura." (PMID 34572485, 2021). "The most frequently investigated MMPs in mesothelioma are MMP2 (gelatinase A), MMP9 (gelatinase B), and MMP14." (PMID 34572485, 2021). "Even in non-invasive mesothelioma cells wherein MMP-2 gene expression was silenced, MMP-2 promoter activities were considerably detected." (PMID 33028834, 2020). "Here we found that the matrix metalloproteinase-2 (MMP-2) was required for the invasion of mesothelioma cells in the collagen matrix and the gene expression of MMP-2 was correlated with the invasive phenotype." (PMID 33028834, 2020). "Knockdown of CBX6 in mesothelioma cells altered sets of genes that potentially participate in migration and invasiveness, including MMP-2." (PMID 33028834, 2020). "TCGA analysis of human mesothelioma samples further supported the correlation between CpG methylation status in this specified region and MMP-2 expression levels." (PMID 33028834, 2020). "Knockdown of PRC component chromobox 6 (CBX6) promoted MMP-2 expression and invasion of mesothelioma cells." (PMID 33028834, 2020). "Using shRNA-mediated knockdown of PcG proteins, we found CBX6 as a major PcG silenced MMP-2 in non-invasive mesothelioma cells." (PMID 33028834, 2020). "To determine mechanism for MMP-2 gene regulation, we first examined MMP-2 promoter activities by reporter gene assays in mesothelioma cells." (PMID 33028834, 2020). "Collectively, these results suggest that the dysregulation of epigenetic silencing of MMP-2 is involved in mesothelioma progression to invasive tumors." (PMID 33028834, 2020). "This study investigated the influence of MMP2, MMP9, and MMP14 gene polymorphisms on time to progression and overall survival in mesothelioma patients." (PMID 29138529, 2017). "In contrast, a recent study indicated that inhibition by integrin β1-targeting siRNA did not affect 3-D collagen-induced cell surface localization of MT1-MMP or MMP-2 activation in mesothelioma cells." (PMID 25317077, 2014). "Cytokines and inhibitors have an up- or down-regulatory effect on MMP2 expression in mesothelioma, suggesting the clinical value of targeting MMP2 for management of mesothelioma and its pathogenesis." (PMID 22737246, 2012). "However, there is a clinical application to MMPs in mesothelioma, since increasing MMP2 activity suggests poorer survival and is correlated with clinical parameters of diseases progression, such as weight loss." (PMID 34572485, 2021). "Mesothelioma pro-MMP2 and active MMP2 levels were significantly higher than MMP9 levels." (PMID 34572485, 2021). "This study clearly indicated that MMP2 is the most abundant gelatinase in mesothelioma, so it may play an important role in tumor growth and metastasis." (PMID 34572485, 2021). "Active MMP2 levels were significantly higher in mesothelioma than in uninflamed pleura." (PMID 34572485, 2021). "Knockdown of CBX6 promoted MMP2 expression and invasion of mesothelioma cells." (PMID 34572485, 2021).
mesothelioma (continued). "Since MMP-2 is essential for collagen invasion as we shown here, MMP-2 upregulation in invasive mesothelioma cells, which might be caused by CBX6 degradation, would contribute mesothelioma invasion." (PMID 33028834, 2020). "Although MMP-2, MMP-9, and MT1-MMP have been implicated in mesothelioma invasion, our results demonstrated that MT1-MMP-mediated MMP-2 activation is essential for collagen invasion and there is strong correlation between MMP-2 gene expression and invasive phenotype." (PMID 33028834, 2020). "Thus, MMP-2 is definitively responsible for collagen invasion of mesothelioma cells and MMP-2 expression is correlated with the invasive phenotype." (PMID 33028834, 2020). "Interestingly, the active form of MMP2 was significantly increased in mesothelioma spheroids compared to monolayers." (PMID 22737246, 2012). "Interestingly, MMP2 has already been suggested as an important molecule involved in mesothelioma pathogenesis and proposed as a marker for mesothelioma." (PMID 22737246, 2012). "Thus MMP-2 gene expression was epigenetically silenced in non-invasive mesothelioma cells." (PMID 33028834, 2020). "Thus, the knockdown of CBX6 upregulated MMP-2 expression and mesothelioma invasion." (PMID 33028834, 2020). "Keeping in mind the potential role of MMPs in mesothelioma and considering that only expression of MMP2, MMP9, and MMP14 has been studied in mesothelioma, we set out to perform a study exploring genetic variability of these genes." (PMID 29138529, 2017). "Different MMPs (MMP2, MMP9, MMP11, and MMP14) and their expression were studied in the mesothelioma tissue, but only a few have been prognostically significant." (PMID 29138529, 2017). "Mesothelioma MSTO-211H cells showed two bands, an intense band corresponding to MMP-2 and a faint band corresponding to MMP-9, which was significantly enhanced with PMA treatment." (PMID 23563849, 2013). "Immunohistochemical analysis of tumor tissues obtained from three patients with malignant mesothelioma indicated that MMP-2 was detected in mesothelioma cells rather than in stromal cells." (PMID 33028834, 2020). "The crucial involvement of MMP-2, MMP-9, and MT1-MMP in mesothelioma invasion has been investigated, but the molecular events leading to the acquisition of the invasive behavior remains unknown." (PMID 33028834, 2020). "It is possible that the mesothelioma study did not achieve sufficient abrogation of β1 integrin to reduce MMP-2 activation at 48 hours after transfection integrin β1-targeting siRNA where β1 integrin is not complete knockdown." (PMID 25317077, 2014). "Importantly, CpGs in this region were hypermethylated in normal mesothelial cells (MeT-5A) and non-invasive mesothelioma cells (H28, H2052, Meso-4), while these were hypomethylated in invasive mesothelioma cells (JMN-1B, Meso-1, EHMES-1), indicating a strong correlation with MMP-2 gene expression." (PMID 33028834, 2020). "We show in this work that MMP2, BAFF/BLyS/TNFSF13B, RANTES/CCL5 and TNFAIP6/TSG-6 are highly expressed in 3D mesothelioma but not in monolayers." (PMID 22737246, 2012).
metastatic melanoma (14 papers, 2010 to 2025). A melanoma that has spread from its primary site to another anatomic site. "Loss of AP-2α in metastatic melanoma is directly linked to overexpression of melanoma cell adhesion molecule MCAM/MUC18, protease-activated receptor-1 (PAR-1), matrix metalloproteinase-2 (MMP-2), and loss of tyrosine-kinase receptor c-KIT." (PMID 20805990, 2010). "For example, claudin-1 was found to activate MMP-2 through the activation of the c-Abl-protein kinase Cδ (PKCδ) signaling pathway, while increased secretion of MMP-2 correlated with cytoplasmic expression of claudin-1 in metastatic melanoma cells in a PKC-dependent manner." (PMID 34354941, 2021). "MMP2 has no apparent prognostic value for metastatic melanomas; the mechanism underlying this phenomenon needs further investigation." (PMID 25784655, 2015). "It has been shown that knocking down N-cadherin expression inhibited the activities of MMP-2 and MMP-9, leading to reduced cell invasion in both primary and metastatic melanoma cell lines." (PMID 40806251, 2025).
osteoporosis (14 papers, 2015 to 2025). A condition of reduced bone mass, with decreased cortical thickness and a decrease in the number and size of the trabeculae of cancellous bone (but normal chemical composition), resulting in increased fracture incidence. "In this analysis, MMP2 in the OVXDF group and rats in the OVX group were significantly regulated, and the results showed that MMP2 and osteoporosis were inextricably linked." (PMID 38099525, 2024). "Osteolytic and metabolic changes linked to MMP-2 deficiency affect tarsal, carpal, and phalangeal bones, cause severe arthropathy, osteoporosis, fibrous nodules, distinctive craniofacial defects such as exophthalmos, brachycephaly, and flattened nasal bridges and dwarfism." (PMID 32116759, 2020). "Chronic inflammation, as present in MMP-2 deficiency, alters the balance between osteoclasts and osteoblasts favoring more bone resorption which then leads to osteoporosis." (PMID 33101055, 2020). "Moreover, bioactive cortisol (a factor that exacerbates osteoporosis) was also elevated in MMP-2 deficient mice and patients." (PMID 33101055, 2020). "Thus, further research is needed to establish cortisol as a target for therapeutic intervention in reducing osteoporosis in MMP-2 deficiency." (PMID 33101055, 2020). "The enzyme analysis results of all these studies revealed that MMP2, MMP9, TIMP1, and TIMP2 were low and cathepsin K was high in MPS III patients, and that the patients had low bone density and increased osteoporosis risk." (PMID 40104299, 2025). "Previous clinical studies showed that serum MMP2 concentrations were significantly higher in postmenopausal women with osteoporosis than in normal controls." (PMID 38099525, 2024). "In mice in a prednisolone-induced osteoporosis model, a histochemical analysis of the tibia revealed a prednisolone-induced increased expression in MMP2, 9, and 13 in the bone tissue of mice." (PMID 38099525, 2024). "MMP-2 in the serum of patients with osteoporosis was also significantly elevated compared to patients with osteopenia." (PMID 38138968, 2023). "In experimental glucocorticoid-induced osteoporosis and osteocytic osteolysis, these three enzymes are upregulated in the trabecular bone of the metaphysis whereas MMP-2 and MMP-13 are expressed in the cortical bone diaphysis." (PMID 32116759, 2020). "While Mmp2-null mice have osteoporosis, Mmp9-null and Mmp13-null mice exhibit enlarged hypertrophic zones and osteopetrosis." (PMID 28158191, 2017). "Interestingly, IMB-R38 treatment significantly decreased mRNA levels of Mmp9, Mmp13, Mmp2, and Il-6, which play a vital role in both osteoporosis and inflammation." (PMID 41465573, 2025). "In addition to confirming the mechanism of the action of MMP2 in primary osteoporosis, the SUN study confirmed its similar involvement in the pathological process of glucocorticoid-induced osteoporosis." (PMID 38099525, 2024). "Second, we only evaluated the effect of a small set of MMPs on BMD, but missed such types as MMP-2, -9 and -13, which might be in relation to osteoporosis according to previous studies." (PMID 34868227, 2021). "Altogether, since Mmp2 elevated levels were detected in sera of osteoporotic patients, the present study further strengthens a previously suggested engagement of Fas/FasL system in osteoporosis." (PMID 30283358, 2018). "It is, therefore, reasonable to infer that MMP2 could be a therapeutic target for the treatment of osteoporosis.SORBS1 refers to the insulin signaling molecules expressed in fat and skeletal muscle that is involved in the regulation of signaling pathways within the cytoskeleton." (PMID 38099525, 2024). "Therefore, MMP2 and MMP9 are expected to increase in osteoporosis activities." (PMID 40104299, 2025).
thoracic aortic aneurysm (14 papers, 2006 to 2025). An aneurysm formed in the wall of the proximal portion of the descending aorta proceeding from the arch of the aorta. "In another recent case: control analysis of miRNA differentially expressed in human subjects with thoracic aortic aneurysm identified miR-29 targeting a 3’UTR of the MMP-2 gene." (PMID 24627221, 2014). "Elastin and collagen degradation in thoracic aortic aneurysms is mediated by MMPs, particularly the gelatinases, MMP-2 and MMP-9." (PMID 16722611, 2006). "Research has shown that MMP-2 deficiency leads to inhibition of the activation of transforming growth factor-β (TGF-β) and the Smad2/3 pathway, emphasizing the interaction between MMP-2 and other signaling proteins involved in the progression and occurrence of thoracic aortic aneurysm." (PMID 39769454, 2024). "Matrix metalloproteinases (MMPs), particularly MMP-2 and MMP-9, are activated and increased in expression in thoracic aortic aneurysm (TAA)." (PMID 38469141, 2024). "Despite the established matrix-degrading function of MMP2 in AAA formation, Ang II-infused MMP2−/− mice showed more severe dilation of the thoracic aorta and thoracic aortic aneurysm." (PMID 35414069, 2022). "In the aorta, aggrecan degradation is likely to be due to increase in the activity and expression of aortic MMP-2, MMP-9 and Calpain-1 with advancing age33–37, whilst increased ADAMTS levels promote thoracic aortic aneurysm progression." (PMID 29867203, 2018). "These study findings suggest that the dysregulation of MMP‐2 and MMP‐9, two key enzymes involved in the degradation of the ECM within the aortic wall, may play a crucial role in the pathogenesis of thoracic aortic aneurysms and dissections." (PMID 40581980, 2025). "Surprisingly, there was also a negative correlation between miR-29a and total MMP2 expression in human thoracic aortic aneurysm tissue." (PMID 28164126, 2017).